Y_RNA (Y RNA )
Gene: Miscellaneous RNA gene on chromosome 12 (107,650,789 to 107,650,892, forward strand). Ensembl gene ENSG00000222160.
Homologues: Orthologues: chimpanzee Y_RNA (100% identical), guinea pig Y_RNA (74% identical). Paralogues in human: Y_RNA (84% identical), Y_RNA (83% identical), RNY3 (82% identical), Y_RNA (82% identical), Y_RNA (81% identical), Y_RNA (80% identical), RNY3P1 (79% identical), RNY3P14 (79% identical), Y_RNA (79% identical), RNY3P2 (78% identical), Y_RNA (78% identical), Y_RNA (77% identical), and 93 more.